HDGF (heparin binding growth factor)
Diseases named in the same sentence as HDGF in open-access papers (continued):
Sharing a sentence is not in itself a finding about the gene and the disease.
tumor (continued). "YBX1 binding protects the transcript from degradation, leading to higher HDGF protein levels and increased tumor cell growth, invasion, and metastasis." (PMID 41301491, 2025). "It is particularly noteworthy that in EGFR-mutant NSCLC models, the combination of anti-HDGF antibodies and osimertinib not only achieved complete or near-complete tumor regression but also markedly prolonged progression-free survival." (PMID 41278276, 2025). "In osimertinib-treated tumors, however, all the surviving tumor cells showed strong nuclear staining, suggesting an increase in the level of HDGF expression." (PMID 39041204, 2024). "The methylation of HDGF mRNA mediated by METTL3 enhances mRNA stability and was directly recognized by the m6A reader IGF2BP3 that bound to the m6A site of HDGF mRNA, which facilitates subsequent tumor growth and liver metastasis in GC." (PMID 39009956, 2024). "In IHC of naïve tumor, HDGF staining was seen in the nucleus of most of the tumor cells with intensity ranging from weak to medium to strong." (PMID 39041204, 2024). "The downregulation of hsa-miR-195-5p results in the overexpression of MMP14 and HDGF, which act as tumor promoters and are both targeted by hsa-miR-195-5p." (PMID 38342922, 2024). "In established TM00219 tumors (257–427 mm3), the humanized anti-HDGF antibody H3 was given at 13 mg/kg concurrently with the start of osimertinib dosing and subsequently maintained at twice per week till tumor relapse or up to 200 days." (PMID 39041204, 2024). "In this study, we investigated the role of HDGF in promoting tumor tolerance to osimertinib using two PDX tumor models of NSCLC: TM00199 and TM00219." (PMID 39041204, 2024). "In several tumor cell lines, HDGF has been shown to activate PI3K/Akt signaling through interaction with cell surface receptor or activate MAPK/ERK signaling by enhancing KRAS expression." (PMID 39041204, 2024). "Surprisingly, concurrent administration of an anti-HDGF antibody at the start of osimertinib treatment led to tumor regression exceeding 98%." (PMID 39041204, 2024). "In this intricate process, HDGF plays a crucial role by inducing tumor tolerance, partly through the activation of MAPK/ERK and PI3K/AKT pathways." (PMID 39041204, 2024). "In pancreatic stellate cell (PSC), HIF-1α can induce the expression of HDGF and the increased level of HDGF shows anti-apoptotic and pro-fibrotic effects, which can maintain tumor lesions." (PMID 38725864, 2024). "An alternative explanation of the data is that HDGF plays a role in maintaining tumor cell activity." (PMID 37827291, 2023). "We confirmed the results of recombinant HDGF and TNFα using 3-D organoids, but it took about 2–3 months by xenotransplantation assays, and the tumor size was always very small." (PMID 37047540, 2023). "Intriguingly, while nuclear HDGF involves in glycolysis, secretory HDGF in the TME promotes tumor angiogenesis." (PMID 37280679, 2023). "As a biomarker of tumorigenesis, HDGF is not only an inducer of tumor progression but also an indicator of tissue inflammation." (PMID 37827291, 2023). "Conversely, in gefitinib-sensitive PC-9 xenografts, stable HDGF expression resulted in rapid tumor growth compared with the control group, but the tumor-promoting effect of HDGF was lessened by 10 mg/kg gefitinib administration." (PMID 37301856, 2023). "Conversely, HDGF overexpression markedly augmented PC-9 tumor volume and weight when compared with the control group." (PMID 37301856, 2023). "Ki-67 and HDGF expression in mouse tumor tissues exhibited similar patterns as tumor volume and weight in H1975 and PC-9 xenografts." (PMID 37301856, 2023). "Compared with the control group, tumor growth was significantly decreased by both HDGF sgRNAs, and the inhibitory effect was more obvious in the sgRNA2 group, indicating that HDGF knockdown restricted H1975 tumor development." (PMID 37301856, 2023).
tumor (continued). "HDGF has been reported to be involved in cancer cell growth, angiogenesis, anti-apoptosis, and tumor metastasis." (PMID 37301856, 2023). "Pleiotrophin (PTN) is a heparin-binding growth factor of the family of midkine, a tumor promoting factor." (PMID 36614248, 2023). "Meanwhile, Western blotting confirmed that HDGF expression was inhibited by both sgRNAs in H1975 tumor tissues." (PMID 37301856, 2023). "Secreted HDGF promotes tumor angiogenesis, while nuclear HDGF activates glucose transporter type 4 (GLUT4) and enolase 2 (ENO2) expression, which is followed by increased glycolysis in GC cells." (PMID 38053093, 2023). "To explore the mechanisms of HDGF-driven gefitinib resistance, we determined the gefitinib resistance-associated proteins p-Akt and p-ERK in NSCLC cells and mouse tumor tissues." (PMID 37301856, 2023). "In detail, knockdown of HDGF inhibited tumor growth in H1975 cells in vitro and in vivo, while overexpression of HDGF retarded the gefitinib response in PC-9 cells." (PMID 37301856, 2023). "Nevertheless, HDGF overexpression still resulted in faster tumor growth than observed in the control group after gefitinib treatment (P < 0.05), implying that HDGF augmentation abrogated gefitinib efficacy to some extent." (PMID 37301856, 2023). "Our study provides a link between the tumor-suppressive miR-129-5p and the mitogenic growth factor HDGF that is frequently overexpressed in HCC." (PMID 35578240, 2022). "Ectopic expression of HDGF effectively abolished the G3BP2 depletion-mediated inhibitory effect on tumor cell migration." (PMID 34782720, 2022). "We next sought to analyze the impact of HDGF downregulation on tumor-relevant functions by performing cell viability and apoptosis measurements after HDGF knockdown." (PMID 35578240, 2022). "Our in vitro results suggested a Wnt signaling status-dependent transmission of HDGF’s tumor-suppressive effects in HCC cell lines." (PMID 35578240, 2022). "The m5C-related factors form a tumor microenvironment suitable for migration and metastasis of various cancer cells by regulating some known tumor promoters, such as HDGF, TGF-β, FGF2, and G3BP1." (PMID 35464855, 2022). "In particular, accumulating studies have shown that HDGF plays an important role in driving tumor cell metastasis." (PMID 34782720, 2022). "This is the first study considering the Wnt status-dependent tumor-suppressive effects of miR-129-5p and HDGF knockdown in HCC." (PMID 35578240, 2022). "Tumor angiogenesis was promoted by Hepatoma-derived growth factor (HDGF) upregulation, while nuclear HDGF activated GLUT4 and ENO2 expression and increased metastasis in GC cells." (PMID 35186927, 2022). "HDGF promotes tumor growth and liver metastasis by promoting tumor angiogenesis on the one hand and activating the expression of GLUT4 and ENO2 on the other hand, which results in promotion of glycolysis in GC cells." (PMID 35155557, 2022). "Hepatoma-derived growth factor (HDGF) is another biomarker that has been associated with poor outcome and tumor progression in patients suffering CCA." (PMID 35205774, 2022). "MDK (Midkine), a heparin-binding growth factor, is abnormally overexpressed in several human malignancies playing a key role during tumor development." (PMID 33800494, 2021). "It is reported that MMP14 act as a tumor promoter and HDGF is involved in the regulation of cell apoptosis, angiogenesis, invasion and metastasis and they were targeted by miR-195-5p." (PMID 33906322, 2021). "The activation of the NSUN2/YBX1/HDGF axis was proven to promote cell growth, tumor progression and metastasis." (PMID 34512153, 2021).
tumor (continued). "Knockdown of IGF2BP3 markedly reduced the expression of HDGF mRNA and suppressed tumor growth in GC." (PMID 32276589, 2020). "The expression of SNHG3 and HDGF was upregulated while miR-384 was downregulated in tumor tissues, compared with normal tissues." (PMID 33817254, 2020). "An immunohistochemical evaluation suggested that there is a significant relationship between the expression of HDGF and tumor growth." (PMID 32545762, 2020). "In NSCLC cell lines and patient specimens, miR-497 has been found downregulated and has been reported to inhibit cell proliferation in vitro and tumor growth in vivo by targeting the hepatoma-derived growth factor (HDGF)." (PMID 33266470, 2020). "Secreted HDGF drives tumour angiogenesis, while nuclear HDGF elevates ENO2 and GLUT4 levels, followed by a potentiation of the glycolysis ability, resulting in GC growth and liver metastasis." (PMID 33029866, 2020). "Further, secreted HDGF promotes tumor angiogenesis, while nuclear HDGF activates glycolysis-related proteins, including enolase 2 (ENO2) and solute carrier family 2 member 4 (GLUT4), followed by an increase in glycolysis to cause tumor growth in GC." (PMID 32429972, 2020). "Together, these data indicated the tumor-promoting role of the LINC00958/miR-3619-5p/HDGF axis in HCC." (PMID 31915027, 2020). "It is apparent that SNHG3 and HDGF expression was upregulated while miR-384 was downregulated in tumor tissues." (PMID 33817254, 2020). "In previous studies, we also observed that miR-133a-3p, miR-5188, miR-3188, miR-374a, and miR-296-3p, respectively were modulated by VPS33B, HBx, FOXO1, PDCD4, and HDGF involving in the tumor pathogenesis induced by these genes." (PMID 32641685, 2020). "Characteristics such as promoting growth, suppressing differentiation, and exhibiting angiogenic properties, suggest a role for HDGF in cancer induction and tumor progression." (PMID 31032220, 2019). "Ectopically expressed miR-214 inhibits xenograft tumor growth and microvascularity of tumors and their surrounding tissues via targeting and suppressing its downstream target gene, hepatoma-derived growth factor (HDGF)." (PMID 31640265, 2019). "HDGF is ubiquitously expressed in normal tissues and tumor cell lines that exhibit growth factor properties." (PMID 31032220, 2019). "The mice injected with shHDGF-Ishikawa and shHDGF-RL95-2 cells had smaller tumor burdens and displayed lower expression of HDGF, Ki67 and proliferating cell nuclear antigen (PCNA) in tumor tissues relative to the controls." (PMID 31032220, 2019). "Human hepatoma-derived growth factor (HDGF) is highly expressed in the developing heart, tumour cell lines and normal tissue ubiquitously with mitogenic and angiogenic activities." (PMID 29321480, 2018). "Although HDGF has been identified as an oncogene, the mechanism by which HDGF promotes tumor development is not fully understood." (PMID 30004626, 2018). "HDGF shows proliferative activity, and expression of HDGF has been reported in many different tumor types and correlated with prognosis." (PMID 29795395, 2018). "Our analysis revealed for the first time that MGUS is characteristic by low levels of TGFB1 and high levels of midkine, a heparin-binding growth factor involved in angiogenic and anti-apoptotic functions and tumor expansion in various cancers." (PMID 29050213, 2017). "EGFR receptors include AR, EGF, TGF-α, epiregulin, heparin-binding EGF (HB-EGF) and Hepatocarcinoma cell-derived hepatoma-derived growth factor (HDGF), have been confirmed to mediate tumorigenesis and promote tumor progression." (PMID 26451607, 2015). "Tumor growth was significantly inhibited in HDGF-siRNA treatment group compared with the control group (p = 0.0277)." (PMID 26296979, 2015). "Downregulation of miR-214 contributes to HCC via activation of the HDGF paracrine pathway for tumor angiogenesis." (PMID 26231037, 2015).
tumor (continued). "The histological studies using human HCC samples unveil the positive correlation of NCL expression with tumour grade, vascular invasion and HDGF expression in HCC patients." (PMID 25938538, 2015). "HDGF overexpression is correlated with tumor progression and poor survival outcome for HCC patients." (PMID 25938538, 2015). "In previous studies, HDGF had been reported as an important tumor metastasis promoter by facilitating epithelial-mesenchymal transition and cell metastasis." (PMID 24692842, 2014). "The expression of HDGF was significantly increased compared with adjacent non-tumor tissue samples (p < 0.001)." (PMID 25421244, 2014). "HDGF expression in tumor tissues was examined using immunohistochemistry (IHC), and its association with clinicopathological parameters was evaluated." (PMID 24692842, 2014). "Hepatoma-derived growth factor (HDGF) is a protein which is highly expressed in a variety of tumours." (PMID 23305559, 2013). "HDGF has been reported to be overexpressed in a wide variety of tumours and its expression correlates with an unfavourable prognosis for cancer patients." (PMID 23305559, 2013). "Similar to HDGF nucleolin was reported to play an important role in tumour biology by regulating proliferative, apoptotic and angiogenic signalling pathways." (PMID 23305559, 2013). "In multiple studies it has been shown that elevated levels of HDGF in different types of tumours correlate with metastatic potential, increased malignancy and thus, a unfavourable prognosis for patients." (PMID 23305559, 2013). "We also examined tumor cell invasion following treatment with rHDGF (10 ng/mL) or gene knockdown with HDGF shRNA gene delivery." (PMID 23536873, 2013). "Over the last decade, HDGF research focuses on its possible role in tumour induction and/or tumour progression and metastasis." (PMID 23305559, 2013). "Beside its proliferative activity HDGF was reported to have angiogenic as well as antiapoptotic activity thereby making it an interesting candidate for tumour therapy." (PMID 23305559, 2013). "Pleiotrophin (PTN) is a heparin-binding growth factor with significant role(s) in tumour growth and angiogenesis." (PMID 22423616, 2012). "We found the most highly up-regulated gene in PAD2-depleted cells to be pleotropin (PTN), a secreted heparin-binding growth factor believed to be important in tumor angiogenesis and also described as a proto-oncogene." (PMID 22911765, 2012). "So far, the influence of HDGF on tumors was studied by si-RNA mediated or antibody-mediated reduction of HDGF in tumor mouse models." (PMID 22014102, 2011). "On the other hand, in vitro and in vivo experiments showed that a reduction of HDGF in transformed cells or the injection of HDGF specific antibodies resulted in slowed tumor growth, reduced number of blood vessels, and increased rate of apoptosis." (PMID 22014102, 2011). "The accordant results showed, that a reduction of HDGF in tumor cells resulted in the formation of smaller tumors, reduced tumor angiogenic and metastatic capacity, and an improved response to chemotherapeutic treatment." (PMID 22014102, 2011). "Instead, the here presented results in combination with previous findings point to a possible role of the growth factor in cell differentiation and suggest that HDGF promotes tumor progression after secondary upregulation." (PMID 22014102, 2011). "The subsequent functional studies demonstrated that knocking down the endogenous expression of HDGF led to significant reduced in vitro cell growth, transformation, migration, invasion, as well as in vivo xenograft tumor formation." (PMID 20846397, 2010). "HDGF was more abundantly expressed in HCC than in the tumor free adjacent liver tissues in human and murine samples." (PMID 27942274, 2009). "Overexpression of HDGF dramatically abolished the tumor suppressive role of miR-195 in NSCLC cells." (PMID 39963112, 2025).
tumor (continued). "Additionally, METTL3 can regulate the stability of HDGF mRNA through m6A methylation, promoting tumor growth and liver metastasis in GC." (PMID 41584846, 2025). "Therefore, validating the tumor-promoting role of HDGF using nude mouse xenograft models represents our primary follow-up objective." (PMID 41278276, 2025). "On the basis of correlation analysis, we propose that HER2 + IBC tumour cells can influence the activation and differentiation process of B cells by upregulating the expression of the heparin-binding growth factor PTN, which in turn promotes the production of TNF by B cells." (PMID 40624675, 2025). "Furthermore, in vivo experiments showed that, compared with HT29 WT tumors, HDGF KO significantly reduced tumor volume and weight, and enhanced sensitivity to 5-FU or oxaliplatin." (PMID 40001585, 2025). "In addition, the upregulation of METTL3 stabilizes HDGF mRNA through increased m6A modifications, enhancing tumor proliferation, metastasis and resistance to targeted drugs." (PMID 41584846, 2025). "Recent research indicates that HDGF is abnormally expressed in many types of cancer, where it promotes tumor progression by regulating biological processes such as proliferation and differentiation, metastasis, apoptosis, angiogenesis, and therapeutic resistance." (PMID 40001585, 2025). "Weak cytoplasmic staining of HDGF was also observed in naïve tumor cells." (PMID 39041204, 2024). "In cultured NSCLC cells or xenograft tumor, the expression of HDGF is positively correlated with the activation of these pathways and the resistance to EGFR TKI; knocking down HDGF diminishes the activation of these pathways and sensitizes the cells to TKI inhibition." (PMID 39041204, 2024). "The interplay between the PWWP domainand C140 domains in determining DNA-binding specificity could pavethe way for new therapeutic strategies targeting HDGF’s rolein tumor growth and metastasis." (PMID 39091133, 2024). "As HDGF could promote the expansion of hematopoietic or cancer stem cells, it is possible that tumor cells with higher HDGF expression exhibit more stem cell–like features and are thus more tolerant to TKI." (PMID 39041204, 2024). "Blocking HDGF promotes tumor regression and significantly extends survival in tumor-bearing mice." (PMID 39041204, 2024). "Higher levels of HDGF in plasma or tumor tissue also indicated gefitinib resistance." (PMID 37301856, 2023). "More interestingly, the enhanced level of circMYH9 in CRC cells has been shown to increase hepatoma-derived growth factor (HDGF) mRNA stability by sponging the tumor suppressing miRNA miR-761, leading to increased cancer cells survival against the anticancer compound Baicalin." (PMID 36900344, 2023). "Additionally, IL-1β and hepatoma-derived growth factor (HDGF) trigger MSCs to secrete tumor-promoting cytokines that support tumor progression." (PMID 37626931, 2023). "Meanwhile, MTE could disturb the interaction between tumor-associated macrophages and NSCLC cells by targeting HDGF." (PMID 37301856, 2023). "Western blot assays also confirmed higher levels of HDGF in PC-9 tumor tissues." (PMID 37301856, 2023). "Therefore, studies have indicated that HDGF upregulation is found in numerous types of tumors, and its intensity and distribution in tumor cells are positively correlated with clinicopathological signatures." (PMID 37827291, 2023). "The METTL3/IGF2BP3/HDGF axis promotes tumor angiogenesis, tumor growth, and liver metastasis." (PMID 37298373, 2023). "Inhibition of HDGF suppressed tumor cell growth both in vitro and in vivo." (PMID 37301856, 2023). "This demonstrates that knockdown of HDGF has tumor-suppressive effects in Wnt-inactive HCCs." (PMID 35578240, 2022). "HDGF promotes tumor growth and liver metastasis by promoting tumor angiogenesis." (PMID 35155557, 2022).